CXCR2 (C-X-C motif chemokine receptor 2)
Diseases named in the same sentence as CXCR2 in open-access papers (continued):
Sharing a sentence is not in itself a finding about the gene and the disease.
gastric cancer (continued). "CXCL1 was expressed in the cytoplasm of gastric cancer cells, and CXCR2 was expressed on the cell membrane and in the cytoplasm of fibroblasts." (PMID 28575019, 2017). "Correlation between the expression of CXCL1 in cancer cells and that of CXCR2 in stromal cells and clinicopathologic features in 270 patients with gastric carcinoma." (PMID 28575019, 2017). "Immunohistochemical staining section analysis demonstrated that CXCR2 expression was mainly located in the cytoplasm of gastric carcinoma cells." (PMID 26497045, 2015). "High expression of migration-related factors, such as cyclooxygenase 2 (COX-2), Vascular endothelial growth factor (VEGF), CXC chemokine ligand (CXCL)-8, chemokine (C-X-C motif) receptor (CXCR)-2, and CXCL-1, are associated with gastric cancer progression." (PMID 22479608, 2012). "Previously, our group showed a significant association of CXCR2 and CXCL1 over-expression (n = 116) with gastric cancer progression." (PMID 22479608, 2012). "In recent years, several studies have shown that IL-8 and CXCR2 are overexpressed in a range of human cancers including renal, prostate, pancreatic, colon, nasopharyngeal, and gastric cancers." (PMID 20540789, 2010). "Additionally, macrophages serve as major sources of CXCL1 and CXCL5 in the gastric cancer microenvironment, and promote the migration of gastric cancer cells by activating a CXCR2/STAT3 feed-forward loop." (PMID 41583453, 2025). "Moreover, an increase in CXCR2 expression was reported to be related with poor prognosis in acute myeloid leukemia and invasion of gastric cancer." (PMID 35626430, 2022). "We reported that chemokine C-X-C motif receptor 2 (CXCR2) signaling appears to play an important role in the pathogenic signaling of gastric cancer (GC), and although CXCR2 may have a role in other solid cancers, the significance of CXCR2 in cholangiocarcinoma (CCA) has not been evaluated." (PMID 35377900, 2022). "Furthermore, CXCR2 along with CXCR4 overexpression, was associated with more advanced tumor stages and poorer survival in gastric cancer patients." (PMID 34012923, 2021). "CXCR2-dominated interplays between cancer cells and macrophages drive gastric cancer metastases." (PMID 34840630, 2021). "In another gastric cancer model, MDSCs migration was partially attenuated with CXCR2 inhibitor, which suggested that the CXCL5/CXCR2 axis might play a role in MDSCs’ recruitment." (PMID 34439836, 2021). "The present study suggests that targeting AQP9 and CXCR2 may represent a novel strategy for gastric cancer therapy, in intestinal and diffuse patients respectively." (PMID 34012923, 2021). "Previously, we reported that CXCL1 secreted from gastric cancer cells might play an important role for the migration activity of BM-MCs via CXCL1/CXCR2 signaling." (PMID 28575019, 2017). "A combination of CXCL1 and CXCR2 expression might thus be a useful prognostic indicator, especially for stage I gastric cancer patients." (PMID 28575019, 2017). "Our previous report and this study might suggest the significance of CXCL1/CXCR2 axis on the progression of gastric cancer via the crosstalk between CXCL1 from cancer cells and CXCR2 of stromal fibroblasts." (PMID 28575019, 2017). "Additionally, we also examined the effect of gastric cancer cells on the mRNA level of CXCR2 in BM-MCs." (PMID 28575019, 2017). "Therefore, we focused on CXCL1 expression in gastric cancer cells and CXCR2 expression in stromal fibroblast cells in this study." (PMID 28575019, 2017). "CXCR2 expression was mainly located in the cytoplasm of gastric carcinoma cells." (PMID 26497045, 2015). "Previously, we reported that elevated CXCL1 and CXCR2 in gastric cancer is associated with tumor progression, and that the plasma CXCL1 level may be a useful circulating biomarker for gastric cancer diagnosis." (PMID 22479608, 2012).
gastric cancer (continued). "However, the effect of hypoxia on CXCR2 expression may depend on the selected model, such as in gastric cancer cells, where hypoxia reduces CXCR2 expression." (PMID 35216283, 2022). "Our present results might be explained as follows: CXCL1 secretion by gastric cancer cells occurs first and subsequently stromal cells with CXCR2 expression are recruited into the tumor microenvironment, which is consistent with our previous in vitro and in vivo findings." (PMID 28575019, 2017). "The expression level of CXCR2 is higher in gastric cancer tissues than in adjacent noncancerous tissues and is associated with the extent of tumor differentiation, advanced clinical stage, lymph node involvement, and distant metastasis of gastric cancer." (PMID 27556695, 2016). "CXCL1/CXCR2 signaling promotes the recruitment and accumulation of PMN-MDSCs in gastric cancer, leading to CD8+ T-cell exhaustion." (PMID 41051525, 2025). "The CXCR2 antagonist SB225002 reduced PMN-MDSC aggregation and increased CD8+ T cell infiltration in gastric cancer, further enhancing the antitumor effect of anti-PD-1." (PMID 40722739, 2025). "In gastric cancer, macrophage-derived CXCL5 promotes tumor cell migration through the CXCR2/STAT3 pathway and facilitates chemoresistance via the CXCL5/PI3K/AKT/mTOR pathway." (PMID 38642131, 2024). "Some scholars believe that PADI4 promotes the occurrence and development of gastric cancer by up-regulating TNF-α, CXCR2, and KRT14 in MNK-45 cells and SGC 7901 cells." (PMID 37804426, 2023). "In gastric cancer, PADI4 promotes gastric tumorigenesis and angiogenesis by upregulating CXCR2, KRT14, and TNF-α expression." (PMID 37020554, 2023). "Activation of CXCR2 by CXCL1 and CXCL8 stimulates the proliferation of transformed cells, which leads to gastric cancer." (PMID 37408240, 2023). "In gastric cancer, basal level epithelial cells produced high levels of CXCL2 and CXCL3, which signal through CXCR2, likely recruiting and activating neutrophils during gastritis." (PMID 35757757, 2022). "It was been shown that this crosstalk between CXCR4 and CXCR2 contributed to EMT, migration and invasion of gastric cancer." (PMID 34012923, 2021). "Among the 270 gastric cancers examined, 144 cases (53%) were positive for CXCL1 expression in cancer cells, and 113 cases (42%) were positive for CXCR2 expression in stromal cells." (PMID 28575019, 2017). "The correlations between the clinicopathological features of 270 primary gastric carcinomas and CXCL1 in cancer cells and CXCR2 in stromal cells were analyzed in immunohistochemical studies." (PMID 28575019, 2017). "Gastric cancer tissues show a differential expression of CXCL1 and its receptor CXCR2." (PMID 36614235, 2023). "Indeed, some studies in mouse head and neck cancer and gastric cancer have shown PMN-MDSCs and M-MDSCs can be recruited to spleens or tumors of tumor-bearing mice by CXCR2 or CCR2 signaling, respectively." (PMID 37268941, 2023). "Interestingly, expression of the chemokine (C-X-C motif) receptor 2 (CXCR2) ligands CXCL2 and CXCL3 has been recently shown to contribute to the malignant progression of gastric cancer." (PMID 37193047, 2022). "For these reasons, our results suggest that FPR2, CARD14, CXCR2, EFNA2, CXCR1, AQP9 TRIP13, along with GHRL and KLK11, could be used as promising biomarkers for gastric cancer diagnosis or prognostic evaluation." (PMID 34012923, 2021). "In summary, we have identified a group of genes differentially regulated in the intestinal and diffuse histotypes of gastric cancers with AQP9, CARD14 and CXCR2 impacting on patients’ prognosis, although CXCR2 is the only factor independently impacting overall survival." (PMID 34012923, 2021).
gastric cancer (continued). "Additionally macrophages are also the major sources of chemokines and chemokine receptors in the gastric cancer microenvironment, such as CXCL1 and CXCL5, and promote migration through activating the CXCR2/STAT3 feed-forward circuit." (PMID 33112406, 2020). "It was found that CXCL1/CXCR2 recruits PMN-MDSCs, and S100A8/A9 increases CXCL1 expression in gastric cancer (GC) through the TLR4/p38 MAPK/NF-κB pathway." (PMID 39990210, 2025). "Therefore, activation of either of these two receptors results in an increased expression of CXCR2 and CXCR4, which translates into an increase in gastric cancer cell migration and epithelial-to-mesenchymal transition (EMT) induction of these cells, an effect also significant in metastasis." (PMID 37408240, 2023).
colitis (45 papers, 2011 to 2026). Inflammation of the colon. "Another study also showed CXCR2-mediated MDSC infiltration was required for colitis-associated tumorigenesis." (PMID 38786066, 2024). "Loss of CXCR2 dramatically suppresses colitis-associated tumorigenesis by inhibiting the infiltration of MDSCs into the colonic mucosa and tumors." (PMID 36713833, 2023). "Studies of colitis-associated tumorigenesis and pancreatic ductal adenocarcinoma show a clear role for CXCR2 in tumor growth associated with attenuated MDSC recruitment in Cxcr2–/– mice." (PMID 34124076, 2021). "A previous study demonstrated that CXCR2-expressing MDSCs are essential to promote colitis-associated tumorigenesis." (PMID 31390756, 2019). "Knock-out of CXCR2 hinders the colitis-associated tumorigenesis through inhibiting CD11b+Ly6G+CXCR2+ MDSCs infiltration into colonic mucosa and tumors." (PMID 29383101, 2017). "CXCR2 is required for homing Ly6GhiCD11b+ MDSCs from the circulatory system to tumor tissues in colitis-associated tumorigenesis." (PMID 29383101, 2017). "CXCR2-deficient mice display a lower susceptibility to acute and chronic colitis induced by DSS, with less inflammatory cell infiltration and less ulcer formation." (PMID 27999328, 2016). "For examples, the massive infiltration of granulocytic MDSCs (G-MDSCs) from the circulatory system to colonic mucosa is essential for the development of CAC tumorigenesis since the inhibition of G-MDSCs infiltration via CXCR2 deletion attenuated colitis-associated tumorigenesis." (PMID 38077324, 2023). "Taken together, these data support the notion that IL-22-mediated induction of neutrophil-active chemokines, including CXCL1 and CXCL5 is functionally important in the recruitment of CXCR2+ neutrophils, and that this pathway has an important pathogenic function in colitis." (PMID 36192482, 2022). "The chemokines CXCL1 and CXCL2 and their receptor CXCR2 play an important role in experimental colitis because the deletion of CXCR2 alleviates chronic colitis and associated tumors by inhibiting the penetration of myeloid derived suppressor cells (MDSCs) into the colon mucosa." (PMID 35163326, 2022). "Our hypothesis is also consistent with previous studies where systemic Ly6G+ cell depletion suppresses colitis-associated tumorigenesis and ApcMin/+ adenoma formation through CXCR2-dependent tumor-associated leukocytes." (PMID 30670049, 2019). "Indeed, CXCR2 deficiency halts neutrophil recruitment and CXCR2 inhibition reduces colitis-associated tumorigenesis." (PMID 30917934, 2019). "CXCR2-expressing myeloid-derived suppressor cells promoted colitis-associated tumorigenesis." (PMID 28575019, 2017). "It has been reported that KO of the Ccr5 gene can ameliorate DSS-induced colitis, while KO of Cxcr2 inhibits CRC." (PMID 40749055, 2025). "In a mouse model of TNBS colitis, intervention with the CXCR2 inhibitor SB225002 significantly reduced tissue damage, inflammation and levels of IL‐1β, MIP‐2, iNOS and KC, thereby improving survival." (PMID 39199011, 2024). "Consistently, CXCR2 knockout mice exhibited suppressed colonic inflammation during DSS‐induced colitis, with reduced neutrophil infiltration and downregulation of the NET marker MPO." (PMID 39199011, 2024). "Knockout of CXCR2 attenuated chemically induced colitis and the following tumorigenesis with reduced numbers of neutrophils in tumor sites." (PMID 38786066, 2024). "The major contributor of the colitis-derived tumorigenesis was CXCR2+ MDSCs based on the findings that adoptive transfer of WT MDSCs restored tumor progression." (PMID 38786066, 2024). "Previous findings that CXCR2 depletion strongly affects neutrophil infiltration of the colonic mucosa in mice with experimental colitis strengthens the evidence of this explanation." (PMID 39328405, 2024).
colitis (continued). "The mRNA expression levels of Cxcr2, Chi3l1 and S100a9 in colitis mice were significantly higher than those in control group, especially S100a9, which was consistent with our bioinformatics analysis results." (PMID 38448514, 2024). "In colitis, the activation of CXCR2 can enhance neutrophil chemotaxis and activation, exacerbating the inflammatory response and causing tissue damage." (PMID 38790796, 2024). "We then constructed a colitis model with C.difficile using the CXCR2 inhibitor SB225002 to hinder the migratory capacity of neutrophil." (PMID 36951545, 2023). "As Cxcr2 has previously been shown to regulate G-MDSC infiltration in lower GI/colitis disease models, we assessed the frequency of gastric G-MDSC and non-G-MDSC myeloid cells, in S100a8Cre/+Cxcr2flox/flox versus Cxcr2flox/flox mice, by FACS." (PMID 37744359, 2023). "The RNA array revealed that the CXC chemokines CXCL1 and CXCL5 and their common receptor CXCR2 were among the most significantly different genes between the PAI-1 KO mice with DSS-induced colitis and the WT mice." (PMID 37151884, 2023). "Time point after colitis induction only had an influence on CXCR2 expression; the expression of this protein after 7 days of dietary intervention was higher compared to 3 days (ANOVA, p < 0.001)." (PMID 35163326, 2022). "CXCL1 has been shown to mediate neutrophil recruitment by binding and activating CXCR2 expression on neutrophils during colitis in an M1-Toll-like receptor (TLR) signaling-dependent pathway." (PMID 35392084, 2022). "As shown by ANOVA, the gene expression of Ccr1, Ccr2, Ccr5, and Cxcr2 was higher in the rats with TNBS-induced colitis than in the control group (p < 0.001)." (PMID 35163326, 2022). "CXCL5 is involved in the regulation of CXCR2-dependent neutrophil trafficking and has been associated with the pathology of inflammatory bowel disease in human and DSS-induced colitis in mice." (PMID 29057967, 2017). "Blocking CXCL5 activity using the CXCR2 antagonist SB225002 is highly effective in ameliorating acute experimental colitis and ischemic brain injury." (PMID 26738635, 2016). "MIP-2 expression is correlated with the clinical activity index in human UC and murine DSS colitis, and its receptor, CXCR2, is a major mediator of neutrophil influx in some disease models including acute colitis." (PMID 26497661, 2015). "A small molecule CXCR2 antagonist (SB225002) was effective in ameliorating trinitrobenzene sulfonic acid- (TNBS-) induced colitis in mice, as was an anti-CXCL1 antibody." (PMID 22162719, 2012). "As a result, blocking the IL-8 and CXCR2 signaling pathways may be a useful approach for treating colitis because it can reduce inflammation and tissue damage." (PMID 38790796, 2024). "The direction of changes in the protein expression of CXCR2 is surprising, because this receptor, which is responsible for mediating the migration of neutrophils to the inflammation site, should be high in rats with induced colitis." (PMID 35163326, 2022). "It is also worth noting that in our study, rats from the colitis group consuming feed with beta-glucans showed high protein CXCR2 expression in inflammatory infiltration cells, as well as in intestinal crypt cells, especially near the area of inflammatory infiltrates and heavily damaged mucosa." (PMID 35163326, 2022). "Moreover, the consumption of feed containing low-molar-mass oat beta-glucan resulted in the highest increase in CXCR2 expression in the rats with induced colitis compared to the feed containing high-molar-mass oat beta-glucan." (PMID 35163326, 2022). "The gene expression of these chemokine receptors (Ccr2, Ccr5, and Cxcr2) in the colitis group fed with feed containing high-molar-mass oat beta-glucan (CβGh+) was significantly lower compared to the CβG− group and was at a similar level as in the control group (HβG−) at both time points." (PMID 35163326, 2022).